ZNF626 (zinc finger protein 626)
Description:
May be involved in transcriptional regulation.
Tractability: PROTAC: ubiquitination databases record sites on it.
Gene: Protein-coding gene on chromosome 19 (20,619,939 to 20,661,596, reverse strand). Ensembl gene ENSG00000188171.
Subcellular location: Nucleus
Subcellular location (Human Protein Atlas): Nuclear membrane; Vesicles; Nucleoplasm
Pathways (Reactome):
Gene expression (Transcription): Generic Transcription Pathway
Gene Ontology:
Molecular function: DNA-binding transcription factor activity, RNA polymerase II-specific; RNA polymerase II cis-regulatory region sequence-specific DNA binding
Biological process: regulation of DNA-templated transcription; regulation of transcription by RNA polymerase II
Cellular component: nucleus
Genetic constraint (gnomAD): Loss-of-function variants: 4 observed, 12.1 expected, observed/expected ratio (o/e) 0.33, 90% interval 0.16 to 0.76. The upper end of that interval is the gene's LOEUF score, 0.76, which puts it in group 3 of 6, group 1 being the genes least tolerant of losing a copy. Missense variants: 565 observed, 542.14 expected, observed/expected ratio (o/e) 1.04, 90% interval 0.97 to 1.12. Synonymous variants: 173 observed, 180.42 expected, observed/expected ratio (o/e) 0.96, 90% interval 0.85 to 1.09.
Homologues: Paralogues in human: ZNF737 (77% identical), ZNF66 (74% identical), ZNF92 (70% identical), ZNF723 (69% identical), ZNF253 (68% identical), ZNF675 (67% identical), ZNF257 (66% identical), ZNF98 (66% identical), ZNF680 (66% identical), ZNF273 (65% identical), ZNF431 (65% identical), ZNF430 (64% identical), and 6 more.
Diseases named in the same sentence as ZNF626 in open-access papers:
ZNF626 is named in the same sentence as 5 diseases in open-access papers, as found by Europe PMC text mining. Sharing a sentence is not in itself a finding about the gene and the disease. The quoted sentences say what the papers report.
bipolar disorder (1 paper, 2021). A disorder of the brain that causes unusual shifts in mood, energy, activity levels and the ability to carry out day-to-day tasks. "ZNF626 was pointed out as a candidate gene involved in posttraumatic stress disorder in European American individuals of the United States Army and seems to be associated with bipolar disorder." (PMID 34079582, 2021).
endometrial cancer (1 paper, 2025). Primary or metastatic malignant neoplasm involving the endometrium (mucous membrane that lines the endometrial cavity). "The mechanism in the upregulation of ZNF626 in endometrial cancer may involve its role as a regulator, influencing the growth and apoptosis of cells." (PMID 40002911, 2025). "To validate the differential expression of ZNF626, SLK, and RFWD3 proteins in endometrial cancer (EC), we compared their expression levels in EC tissues with those in normal endometrial tissues." (PMID 40002911, 2025). "Therefore, ZNF626, SLK, and RFWD3 may represent potential therapeutic targets for endometrial cancer." (PMID 40002911, 2025). "Although the roles of ZNF626, SLK, and RFWD3 in endometrial cancer have not been extensively discussed, their biological functions in relation to other tumors are well documented and can provide insights for our study." (PMID 40002911, 2025).
cancer (1 paper, 2025). A tumor composed of atypical neoplastic, often pleomorphic cells that invade other tissues. "While the specific mechanisms remain under investigation, ZNF626 promoting cancer occurrence and development warrants further exploration." (PMID 40002911, 2025).
tumor (1 paper, 2025). "Compared to healthy individuals, the expression levels of ZNF626 and SLK were elevated in EC patients, suggesting that these genes may promote tumor occurrence and development." (PMID 40002911, 2025). "Further relevance analysis between genes and immunization revealed a decreased proportion of memory CD4+ T cells in the tumor group, with RFWD3 positively correlating with M1 macrophages, ZNF626 positively correlating with M2 macrophages, and SLK negatively correlating with M1 macrophages." (PMID 40002911, 2025). "Estrogen promotes cell proliferation and inhibits apoptosis by upregulating ZNF626 and SLK genes and downregulating the RFWD3 gene, while also leading to a decline in memory CD4+ T cells and a shift in macrophage phenotypes from M1 to M2 within the tumor inflammatory microenvironment." (PMID 40002911, 2025).
ZNF626 also shares sentences with these, for which no sentence is quoted: posttraumatic stress disorder (1 paper).